Y_RNA (Y RNA )
Gene: Miscellaneous RNA gene on chromosome 5 (10,337,277 to 10,337,386, forward strand). Ensembl gene ENSG00000252671.
Homologues: Orthologues: chimpanzee Y_RNA (100% identical), macaque Y_RNA (95% identical), guinea pig Y_RNA (90% identical), guinea pig Y_RNA (89% identical). Paralogues in human: Y_RNA (91% identical), Y_RNA (90% identical), RNY1 (89% identical), RNY1P11 (88% identical), Y_RNA (87% identical), RNY1P8 (86% identical), Y_RNA (86% identical), RNY1P10 (85% identical), RNY1P7 (85% identical), Y_RNA (85% identical), Y_RNA (84% identical), RNY1P5 (83% identical), and 98 more.